MGP (matrix Gla protein)
Diseases named in the same sentence as MGP in open-access papers (continued):
Sharing a sentence is not in itself a finding about the gene and the disease.
calcification (continued). "Risk factors for intimal calcification included age, male sex, and smoking, whereas MAC was associated with diabetes and a high ankle-brachial index, and higher levels of circulating inactive Matrix Gla-Protein (MGP)." (PMID 39453431, 2024). "Therefore, MGP is being thoroughly investigated as a predictive and prognostic candidate biomarker and as a therapeutic target for the treatment of vascular calcification and CVD." (PMID 38542487, 2024). "Knockout MGP mice develop spontaneous arterial calcification at an early age." (PMID 37419616, 2023). "There is increasing evidence that genetic variation at the MGP locus could modulate the development of vascular calcification and atherosclerotic disease." (PMID 28821877, 2017). "However, the absence of an association between serum calcification inhibitor levels and coronary calcification/arterial stiffness and the fact that MGP and Klotho undergo post-translational modifications underscore the complexity of this association." (PMID 26147960, 2015). "Other markers, especially ones involved in calcification, such as matrix-GLA-protein and osteopontin, and direct measurement of vascular calcification using cardiac-CT or abdominal x-ray, may add further information to the influence of vitamin D analogs on calcification in dialysis patients." (PMID 25112372, 2014). "Since both the BMP2 and MGP participate in the process of arterial calcification, we observed the expressions of BMP2 and MGP in calcified radial arteries of hemodialysis patients." (PMID 23506394, 2013). "Specific calcium regulatory proteins such as fetuin-A, MGP and OPG act as calcification inhibitors with local and systemic effects and play an important role in the development and prevention of uremic vascular calcification." (PMID 34583616, 2021). "Although the dysregulation of mineral homeostasis and elevated phosphate levels are considered to be key determinants of vascular calcification in CKD, additional key players may strongly contribute, e.g., MGP, which is a powerful inhibitor of tissue calcification." (PMID 32050453, 2020). "In patients with coronary artery calcification was lower than in the control group, which indicates that MGP is not a universal marker or regulator of vascular calcification and might be involved in coronary artery calcification rather than in artery tibial one." (PMID 37441678, 2023).
diabetes (19 papers, 2010 to 2025). "A few studies have evaluated the association between MGP levels and VC in patients with diabetes, although the researchers used different antibodies to determine either circulating dp-ucMGP, t- ucMGP or other conformations of ucMGP." (PMID 24762216, 2014). "Furthermore, although single nucleotide polymorphisms (SNP) of MGP have been associated with outcomes in diabetes and CKD, its association to VC remains obscure." (PMID 32313061, 2020). "This will allow us to infer whether the associations of OPG and MGP levels with diabetes and calcification are causal or just related to disease progression." (PMID 28320782, 2017). "In vessels from patients with diabetes, MGP levels are lower than in normal vessels, which suggest that reduced MGP in diabetes may predispose to calcification." (PMID 21143859, 2010). "Furthermore, reduced γ-carboxylation of MGP has been described in the context of the systemic inflammatory state associated with diabetes which would tend to enhance the concentration of uncarboxylated MGP, thus promoting VC in subjects with diabetes." (PMID 28320782, 2017). "In fact, data have been published in two different transgenic animal models of VC, such as a mouse model with gene deletion for matrix Gla Protein and Ins2Akita/+ mice, a model of diabetes." (PMID 40864097, 2025). "In fact, each of the module components has been implicated with insulin, risk of diabetes or both in some manner (ADAM17, ATL2, MGP, SPLC2, N-methylproline, 3-methylhistidine)." (PMID 36329547, 2022). "Cartilaginous metaplasia of vascular smooth muscle (VSM) is characteristic for arterial calcification in diabetes and uremia and in the background of genetic alterations in matrix Gla protein (MGP)." (PMID 24098781, 2013). "We measured total MGP, but the higher CP of sera from subjects with diabetes might suggest a predominance of the uncarboxylated form." (PMID 28320782, 2017). "Moreover, diabetes may contribute to valve degeneration process by vitamin K-dependent activation of Matrix Gla protein (MGP), an extracellular protein with a relevant role in the process of vascular calcification." (PMID 35071359, 2021). "Other mediators such as MGP present in sera from subjects with diabetes may also have a role." (PMID 28320782, 2017). "On the other hand, γ-carboxyglutamic acid, which constitutes Matrix Gla Protein (MGP), accumulates at vascular calcification sites, and MGP levels are higher in the blood of patients with CKD and diabetes." (PMID 39857396, 2025). "Diabetes and CKD have an inhibitory effect on the protective upregulation of MGP expression, which is a possible pathomechanism for CKD-induced VC." (PMID 26295257, 2015). "The present research studied the effects of menaquinone (MK-7) supplementation on serum dp-ucMGP (dephospho uncarboxylated Matrix Gla Protein), PIVKAII (Prothrombin Induced by Vitamin K Absence), inflammatory markers and body composition indices in type 2 diabetes mellitus (T2DM) patients." (PMID 35365594, 2022). "Serum MGP levels were slightly lower in controls with VC, and though higher in subjects with diabetes, they were not influenced by the presence of VC in this setting." (PMID 28320782, 2017). "Thus, taken together, our data suggest that the CP of serum may be determined by the presence of diabetes, in vivo calcification and elevated OPG and MGP levels." (PMID 28320782, 2017). "Adding other factors including the presence of diabetes, serum creatinine, MDRD-4 eGFR, urinary ACR, serum C-reactive protein (CRP), calcium, phosphate, PTH, RANKL, OPG and MGP did not improve the model significantly." (PMID 28320782, 2017).
breast carcinoma (18 papers, 2014 to 2025). "For example, in the normal sample, FNBP1 was co-expressed with MGP, whose down-regulation is associated with better survival in breast cancer (scLink’s correlation = 0.77, adjusted P = 0)." (PMID 34252628, 2021). "In breast cancer cell line, both variants of MGP proteins was clearly visible although isoform with molecular weight of 15.32 kDa seems to be expressed at much higher level." (PMID 30257426, 2018). "MGP appeared as the top molecule in LECs upregulated by both different types of breast cancers in vivo and cancer cell lines in vitro." (PMID 41249124, 2025). "In contrast, Li demonstrated that LGR4 promotes breast cancer metastasis by downregulating MGP expression." (PMID 41395115, 2025). "Here, the authors show that breast cancer can alter the lymphatic endothelial cells (LECs) in the sentinel lymph nodes and that Matrix Gla protein is upregulated in LECs, which in turn promotes cancer cell adhesion." (PMID 41249124, 2025). "Among the upregulated molecules, MGP expression was notably high in metastatic LN LECs of patients with breast cancer, a characteristic that was also observed in cultured LN LECs in the presence of CM of breast cancer cells." (PMID 41249124, 2025). "We further confirmed MGP upregulation on LECs in in vitro cocultures with breast cancer cell lines and in the presence of the conditioned medium (CM)." (PMID 41249124, 2025). "We then focused on MGP, because it was upregulated in the sentinel node LECs of all patients and in the HLECs by CM of all breast cancer cell lines in vitro." (PMID 41249124, 2025). "MGP has been shown to be dysregulated in several tumors, including cervical, ovarian, urogenital, and breast cancers." (PMID 39684309, 2024). "This is best exemplified by breast cancer, where MGP is downregulated in advanced HER2-positive tumors while high levels are associated with the aggressive triple-negative subtype." (PMID 36977707, 2023). "MGP was verified as a reliable marker with extremely high sensitivity in all subtypes of breast carcinoma (87.3–91.2%), which is comparable to TRPS1 and much higher than GATA3 in HER2+ and TNBC subtypes." (PMID 36284362, 2022). "The previous study showed that tumors exhibiting cartilaginous/osseous differentiation such as osteosarcoma and chondrosarcoma had high MGP expression, and they can also metastasize to bone and lung-like breast cancer." (PMID 36284362, 2022). "It would be hard to differentiate metaplastic breast carcinoma with cartilaginous/osseous differentiation from these tumors simply based on MGP positivity." (PMID 36284362, 2022). "It is difficult for MGP itself to differentiate breast carcinoma from hepatocellular or renal cell carcinoma." (PMID 36284362, 2022). "For the first time, we have described the coordinate expression of two MGP isoforms in ovarian and breast cancer cell lines." (PMID 30257426, 2018). "To check if both MGP transcripts are also present in another cancer cell line, we compared their expression between A2780 cell line and breast cancer cell T47D, which is known to express MGP at very high level." (PMID 30257426, 2018). "Overall, these data indicate that breast tumor-induced MGP upregulation on LECs may play roles in inhibiting LEC migration but increases their interaction with breast cancer cells." (PMID 41249124, 2025). "Consistent with the functional importance of MGP in physiology, deregulated expression of MGP has been reported to correlate with the development of various other pathologies including colorectal, ovarian, lung, and breast cancers." (PMID 39684309, 2024). "Additionally, MGP is involved in a variety of cancers trough the overexpression of the MGP gene in breast cancer cells, in primary renal, testicular, and prostate carcinomas, in ovarian and digestive neoplasia, and in glioblastoma." (PMID 38732222, 2024).
breast carcinoma (continued). "When combining GATA3, TRPS1, and MGP, we observed that 797/1201 (66.4%) of the enrolled breast carcinoma cases were positive for all three markers, including 452/565 (80.0%), 238/352 (67.6%), and 107/284 (37.7%) in the ER/PR+, HER2+, and TNBC subgroups, respectively." (PMID 36284362, 2022). "A recent study reported that MGP was overexpressed in various tumors (for example, breast cancer 20, ovarian cancer 21, and gastric cancer 22), which demonstrated that it may be related to the progression and invasion of tumors." (PMID 35414780, 2022). "In the current study, MGP was rarely expressed in lung adenocarcinomas (0.7%), which is lower than the previously reported positivity of GATA3 (∽8%,) and TRPS1 (2–3%,), indicating that MGP is a good marker to differentiate breast cancer from lung adenocarcinoma." (PMID 36284362, 2022). "To verify if expression of both transcript variants is specific only to drug resistant cell lines or can be expressed also in other cancer cell lines, we investigated expression in breast cancer cell line T47D that is known to present MGP expression at high level." (PMID 30257426, 2018). "Up-regulation of MGP mRNA correlates with poor prognosis for breast cancer and gastric cancer." (PMID 27556859, 2016). "Thus, TGF-β and VEGF-induced upregulation of MGP in LECs may be a part of the dissemination mechanism of breast cancer cells in patients." (PMID 41249124, 2025). "Moreover, the matrix Gla protein (MGP), which is a hub gene in the MGP module, uniquely found in the poor prognosis network, has been reported to be among the genes that were upregulated in breast cancer cases where the prognosis was poor." (PMID 35911770, 2022). "Recent studies have shown that overexpressed MGP could be found in various types of cancer, including breast cancer, glioblastoma, primary renal cancer, testicular cancer, prostatic carcinomas, and ovarian cancer, and they suggested that it may be associated with tumor progression and invasion." (PMID 32405535, 2020). "Previous studies show that MGP promotes the breast cancer proliferation, SCGB2A2 and TFF3 can be viewed a valuable predictive biomarker in breast cancer." (PMID 38096269, 2023). "All these data suggest that both MGP and TRPS1 maintain excellent sensitivity in different subtypes of metaplastic breast carcinomas." (PMID 36284362, 2022). "When using MGP, GATA3, and TRPS1 as a novel IHC panel, 93.0% of breast carcinomas were positive for at least two markers, and only 9 cases were negative for all three markers." (PMID 36284362, 2022). "MGP, TRPS1, and GATA3 were positive in 1075/1201 (89.5%), 1109/1201 (92.3%), and 922/1201 (76.8%) breast carcinomas, respectively." (PMID 36284362, 2022). "We further observed that only TRPS1 and matrix Gla protein (MGP) had comparable expression in luminal A/B, HER2-enriched, basal-like and normal-like subtypes of breast cancer." (PMID 36284362, 2022). "We compared MGP, TRPS1, and GATA3 expression in different subtypes of breast carcinoma of (n = 1201) using IHC." (PMID 36284362, 2022). "We next compared MGP, TRPS1, and GATA3 expression in 1201 breast carcinoma cases of different subtypes, including 140 metaplastic breast carcinoma cases, using immunochemistry staining." (PMID 36284362, 2022). "Using mRNA sequencing and proteomic data from TCGA and CPTAC of 24 different solid tumors, we identified six potential genes that are specifically upregulated in breast carcinoma: NAT1, MGP, SCGB2A2, LMX1B, TFAP2B, and TRPS1." (PMID 36284362, 2022). "Similar gene expression results were found in control MG and breast cancer (BC) samples, with heterogeneous levels of GRP-F1, MGP, GGCX, and VKOR and increased expression of OPN and TNFα in cancer cases." (PMID 24949434, 2014). "Thus, breast cancer cell metastasis to LNs remodels LEC subsets in human LNs and escalates MGP expression, potentially facilitating cancer cell dissemination through the lymphatic system." (PMID 41249124, 2025).
breast carcinoma (continued). "Since MGP and TRPS1 showed high expression in luminal A/B, HER2-enriched, TNBC/basal-like, and normal-like subtypes according to the PAM50 subtyping, we selected MGP, TRPS1, and GATA3 for further validation in 1201 cases of breast carcinoma of different subtypes and normal breast tissues." (PMID 36284362, 2022). "Although our IHC data of MGP were collected from primary breast carcinomas, our bioinformatics analysis revealed that MGP mRNA was not significantly changed between paired primary tumors and their metastases, which suggests that similar MGP expression could be found in metastatic breast carcinomas." (PMID 36284362, 2022).
chronic kidney disease (18 papers, 2016 to 2025). Impairment of the renal function secondary to chronic kidney damage persisting for three or more months. "High MGP mRNA expression was associated with an increased risk for the composite of 40% decline in eGFR and end-stage renal disease." (PMID 32824773, 2020). "Kaplan–Meier curves and multivariate Cox analysis showed that interstitial and tubular MGP overexpression was linked with a 40% reduction in eGFR and progression to end-stage renal disease (ESRD) with a Hazard ratio of 3.31." (PMID 30717170, 2019). "Overall, observational studies indicate that low vitamin K status as measured by high dephosphorylated uncarboxylated matrix gla protein concentrations plays a potential role in cardiovascular disease development, particularly in high-risk and chronic kidney disease populations." (PMID 28944098, 2017). "Poor vitamin K status in patients with chronic kidney disease or on hemodialysis not only results from higher needs of activation of MGP in the presence of the increased risk of arterial calcification, but also from lower dietary intake compared with healthy controls." (PMID 26981580, 2016). "Elevated levels of inactive MGP, particularly the dephosphorylated-uncarboxylated form (dp-ucMGP), are strongly associated with increased vascular calcification and adverse cardiovascular outcomes, especially in populations with chronic kidney disease or diabetes." (PMID 41303567, 2025). "Clinical trials have already started to test the efficacy of MGP activation to repair vascular calcification in patients with chronic kidney diseases." (PMID 39086959, 2022). "Evaluation of multiple relationships between fetuin-A, osteoprotegerin and matrix GLA protein and other data in patients with chronic kidney disease." (PMID 34583616, 2021). "One study did not measure the inactive form, but the total concentration of MGP and found a significant reduction in MGP synthesis in patients with aortic valve calcification and chronic kidney disease." (PMID 33808652, 2021). "Likewise, this association between circulating inactive MGP and mortality has been observed in patients with CKD or end-stage renal disease (ESRD) where vascular calcification is generally pronounced." (PMID 35935627, 2022). "Since MGP is expressed in the kidney 5-fold more than in bones, it was hypothesized that MGP expression is altered in chronic kidney disease." (PMID 30717170, 2019). "MGP can be found in the blood stream and there are numerous human and animal studies in which MGP has been used as a marker for different inflammatory diseases that also involve calcification (e.g., coronary artery disease, type 2 diabetes, chronic kidney disease)." (PMID 33808652, 2021). "Other potential players in PXE include the anti-mineralization proteins matrix Gla-protein (MGP) and fetuin-A, which were found to be moderately low in PXE patients and significantly low in chronic kidney disease (CKD) patients." (PMID 40725385, 2025). "Other molecules with a suggested role in PXE are the anti-mineralization proteins matrix Gla-protein (MGP) and fetuin-A, with a suggested link to chronic kidney disease (CKD)." (PMID 28486967, 2017).